MGMT (O-6-methylguanine-DNA methyltransferase)
Diseases named in the same sentence as MGMT in open-access papers (continued):
Sharing a sentence is not in itself a finding about the gene and the disease.
tumor (continued). "MGMT, a DNA repair gene showed methylation in 12.5% of our tumor samples, however we did not observe methylation of MGMT in any of the serum samples (initial set and independent set of cases and controls)." (PMID 28147335, 2017). "Sixteen primary matched tumor and serum were analyzed by quantitative methylation specific PCR (QMSP) to determine analytical and clinical sensitivity of the genes tested (SSBP2, MCAM, ERα, ERβ, APC, CCND2, MGMT, GSTP1, p16 and RARβ2)." (PMID 28147335, 2017). "This proof-of-concept study demonstrates that MGMT can be silenced in multiple cancer cell lines in vitro and in a subcutaneous tumor model with enhanced delivery of AMONs with a non-ablated dose radiation." (PMID 28752860, 2017). "In this way, tumor cells lacking the MGMT repair gene as a result of CpG promoter methylation events are highly sensitive to temozolomide." (PMID 28679371, 2017). "temozolomide could exert its greatest effects in patients with a methylated O6-methylguanine-DNA methyltransferase (MGMT) promoter, by killing sensitive tumor cells." (PMID 28881684, 2017). "In recurrent tumours, ATRX loss was more common in A, AA and sGBM than in rGBM; MGMT loss was not significantly different in A, AA, sGBM and rGBM." (PMID 29026176, 2017). "The MGMT promoter region was methylated in all tumors, indicating that MGMT promoter methylation had not changed at recurrence or in different regions within the same tumor." (PMID 28270234, 2017). "Multiple tumor-related genes are found to be commonly methylated in tissue samples in GC, such as p16, CDH1, RUNX3, MLH1, RASSF1A, p15, APC, DAPK, GSTP1, Reprimo, and MGMT etc.." (PMID 29100425, 2017). "Although molecular information was available for the tumor samples (IDH status, EGFR amplification, PTEN loss, MGMT promoter methylation), no discernable expression patterns were evident among these characteristics likely due to small sample sizes." (PMID 29142297, 2017). "DNA repair enzyme O6-methylguanine-DNA methyltransferase (MGMT), which plays an important role in inducing drug resistance against alkylating agents that modify the O6 position of guanine in DNA, is an attractive target for anti-tumor chemotherapy." (PMID 27347909, 2016). "The distribution of tumor patients with or without MGMT promotor methylation was therefore comparable to the results of studies primarily focusing on this." (PMID 27036027, 2016). "The MGMT promoter methylation status of the tumor was available in 12 patients: 3 patients had MGMT promoter methylated tumors, whereas 9 patients did not." (PMID 27108407, 2016). "Age, tumor localization, gender, KPS and the MGMT promoter methylation status were not identified as risk factors for death in both patient cohorts." (PMID 27108407, 2016). "Though, in a study that examined methylation status of six tumor suppressor genes that included BRCA1, BRCA2, p14, p16, hMLH, and MGMT in breast (n = 23), other tumor (n = 10), and control tissues (n = 4) suggested that BRCA1, BRCA2, and p14 appeared to be under strong epigenetic silencing." (PMID 25641872, 2015). "For HIN-1, RASSF1A and MGMT, the methylation status in tumor-adjacent tissues was higher than that in tumor-distant tissues but the differences were not statistically significant." (PMID 26370119, 2015). "As this is a retrospective study that included patients treated over a long time period, limitations of the study include the lack of O6-methylguanine–DNA methyltransferase (MGMT) methylation status and IDH-1 mutation status for only a portion of tumours." (PMID 26015297, 2015).
tumor (continued). "This survival rate is somehow higher in patients after gross-total resection of tumor, post-operative radiotherapy and concomitant chemotherapy with temozolomide, with GBM carrying promoter hypermethylation of the DNA repair gene MGMT, which occurs in 35-40 % of the cases." (PMID 26530050, 2015). "However, other groups have suggested that MGMT promoter methylation, CRET, intensified local radiotherapy and tumor involvement of the subventricular zone (SVZ) are related with higher rates of distant failure." (PMID 24135848, 2014). "It is evident that in order for a tumour to be responsive to TMZ treatment, it must be deficient in MGMT whilst also proficient in MMR; absence of the latter results in a tolerant phenotype whilst presence of MGMT impedes therapy regardless of MMR status." (PMID 25014631, 2014). "MGMT expression intensity can be considered as an independent prognostic factor for OS, but the influence of percentage CD133 expression on the prognosis for DFS also depends on the tumor stage." (PMID 25015560, 2014). "The peripheric portion of the tumor presented a different profile: 5/84 CpG sites were aberrantly methylated, from which 2 sites were shared with the center portion, that is, MSH3 and MLH1, and 3 sites were exclusively methylated in the tumor periphery, that is, MSH6, MGMT, and APC." (PMID 25544907, 2014). "DAOY, UW228-3 and MED3 MB cell lines all show high MGMT expression while MED1 cells show no MGMT expression by Western blotting, consistent with the observed expression in primary tissue samples from the corresponding tumours." (PMID 24887326, 2014). "Therefore the promotor methylation of the MGMT gene, observed for GBM and various other tumor types, results in an improved outcome for patients, through decreased expression of the dealkylating protein." (PMID 24678590, 2014). "We found that, after postoperative radiotherapy plus chemotherapy, plasma IGFBP-2 levels did not vary significantly with sex, preoperative tumor size and MGMT promoter methylation status." (PMID 24690948, 2014). "In this study of tumors from CRC patients, methylated MGMT promoter was significantly associated with low MGMT expression intensity and poor-differentiation grade but not with OS, DFS, or tumor stage." (PMID 25015560, 2014). "Response of a tumour to TMZ treatment is dependent on two factors: absence of MGMT, the protein which results in inherent resistance, and presence of MMR, the actions of which ultimately lead to cell death." (PMID 25014631, 2014). "They found that high HOXA10 expression was predictive of resistance of treatment, including TMZ treatment, independent of the MGMT methylation status of the tumor." (PMID 25061500, 2014). "In contrast, ROBO1 disconnects N-cadherin from the cytoskeleton in invasive cells, thus increasing their motility; c-MYB induces expression of MGMT, resulting in higher chemoresistance; expression of SOX2 and OLIG2 result in greater stemness and higher capacity for tumour formation." (PMID 23818228, 2013). "There have been several studies correlating various imaging features such as tumor border, enhancement pattern, peritumoral edema, multiplicity, T2 signal and intratumoral cystic change with genetic profiles of GBM, including EGFR and MGMT expression." (PMID 23977117, 2013).
tumor (continued). "To distinguish these tumors by the DNA methylation pattern more simply, we further selected four genes characteristically methylated among different tumor groups: ADRA1D, MGMT, VHL, and THBS1, and performed cluster analysis using the methylation average of 4 genes." (PMID 23638012, 2013). "Although the use of serial sections stained with non-tumour markers for comparison with sections stained for MGMT is undoubtedly helpful, it is not always easy to compare cellular identities between serial sections." (PMID 24252243, 2013). "In addition, we analysed the expression of MLH1, PMS2 and MGMT in primary and recurrent GBM tumour samples obtained from patients with GBM recurrence during TMZ treatment." (PMID 24259277, 2013). "Tumor stage and metastasis correlated with presence of mutant Kras codon 12 (p-values 0.018, 0.044) and methylated RASSF1A (p-values 0.034, 0.044), FHIT (p-values 0.001, 0.047) and MGMT (p-values 0.018, 0.044) genes." (PMID 23573237, 2013). "6/75 tumor samples showed MGMT promoter methylation and negative immunohistochemical nuclear staining of MGMT." (PMID 23110891, 2012). "Similarly, tumor biomarkers known to predict response to adjuvant therapy or overall survival (such as 1p/19q, IDH1/2, and MGMT-methylation) should also be incorporated into future analyses." (PMID 23087667, 2012). "Even in those tumors where MGMT promoter methylation was present, we were able to detect tumor cells with non-methylized MGMT promoter." (PMID 23110891, 2012). "The tumor expressed high level of TOPO2A, TOPO1, MRP1, MGMT, BCRP, ERCC1, RRM1, and TS." (PMID 21776193, 2011). "The frequency of MGMT promoter methylation andMGMT mRNA expression levels was nearly identical in patients undergoing biopsyonly and open tumor resection (data not shown)." (PMID 21365007, 2011). "The results of this analysis are not directly comparable to our own, however, as no assessment was made of intracranial tumour activity, and all measurements of MGMT expression and activity were made after treatment with temozolomide." (PMID 20628383, 2010). "Statistical analysis failed to reveal any significant difference between the MGMT methylation status of primary tumours and metastases or between different metastases of a patient (P=0.49 after adjustment for age and gender)." (PMID 20736948, 2010). "It is noteworthy that in three of the six patients there was discordance between changes in MGMT activity in PBMCs and tumour – two patients had an increase in PBMC MGMT activity and a decrease in tumour levels, and one patient had a decrease in PBMC MGMT activity and an increase in tumour levels." (PMID 20628383, 2010). "In this study, MGMT activity in intracranial tumour samples taken 1–2 weeks after treatment was not clearly higher than pretreatment levels, although the trend is suggestive." (PMID 20628383, 2010). "No clear correlation was noted between depletion of MGMT activity in PBMCs and tumour, nor was there a correlation between depletion of tumour MGMT activity and response rate." (PMID 20628383, 2010). "The MSP assay yields binary data without a quantitative measure of the contribution from unmethylated DNA, which arises from non-neoplastic cells within the tissue or from tumour cells lacking MGMT methylation." (PMID 19536096, 2009). "MS-PCR proposes a clear MGMT promoter methylation status and divides the tumor samples into PCR-positive and –negative cases." (PMID 19274096, 2009). "In about one third of the cases more than 95% of the tumor cells were MGMT-immunopositive, whereas in one third no immunoreactivity was detectable." (PMID 19274096, 2009). "None of the four tumours sampled on day 5 of LM/TMZ treatment had residual MGMT activity, although ELISA showed that MGMT protein was present in all cases." (PMID 19367283, 2009). "In 98 cases (34.4%) a heterogeneous tumor population (1+ and 2+) was detectable consisting of MGMT-immunopositive and negative tumor cells." (PMID 19274096, 2009).
tumor (continued). "No direct association between promoter hypermethylation in MGMT or RASSF1 and age, sex, smoking, alcohol drinking, or tumor stage was observed, in agreement with recently reported data." (PMID 19807915, 2009). "Methylated ADAMTS1, MGMT, and MAL are suitable as markers for early tumor detection." (PMID 19117505, 2008). "MGMT appeared to be more markedly overexpressed in low-grade tumours but MGMT expression was not correlated with a specific phenotype, and its level of expression has no specific prognostic value." (PMID 18506188, 2008). "A higher proportion of patients with resected tumours had the MGMT status successfully assessed due to the lack of a sufficient amount of tumour tissue in stereotactic biopsies." (PMID 17609661, 2007). "A significant correlation was observed between MGMT hypermethylation and the early-stage tumor (P = 0.03), but was not confirmed by multivariate analysis (P = 0.733)." (PMID 16928264, 2006). "We did not attempt to correlate the initial levels or depletion of MGMT in PBMCs with tumour response, since this was a phase I combination trial including patients with different malignancies and multiple prior lines of treatment." (PMID 16136028, 2005). "The genes APC, MGMT; ER, GSTP1, DAPK, RARβ, FHIT and p16 were evaluated pre and post-treatment for DNA promoter methylation and gene expression by MSP (Methylation-Specific PCR) and RT-PCR respectively in each of the tumor samples." (PMID 15862127, 2005). "Two patients showed promoter hypermethylation in all four tumour suppressor genes and negative expression of mRNA in RARβ, MGMT and SYK." (PMID 14970867, 2004). "These methylated CpGs in MGMT-positive tumours, noncancerous tissues except for 4NC and 5NC, and normal tissues never extended beyond the first nine CpGs." (PMID 12592365, 2003). "In that investigation, the MGMT activity measurements were performed on extracts from a single metastasis in each patient without regard to possible tumour heterogeneity." (PMID 14562026, 2003). "Other MGMT-negative tumours, 16C–28C, showed a similar extent of methylation to MGMT-positive tumours and normal tissues." (PMID 12592365, 2003). "This indicates that reduction of MGMT, imposed by the absence of MET, renders mer+ tumour cells more susceptible to alkylating agents." (PMID 9062396, 1997). "Also, we did not observe differences in PFS or OS depending on MGMT promotor status, tumor location or sex." (PMID 41528563, 2026). "It is possible that patients in our cohort expressing MGMT promoter methylation may show up during later stages of their disease, compared to non-methylated, if the tumor is less aggressive." (PMID 41476598, 2025). "Furthermore, MGMT methylation in IDH-mutant astrocytomas may interact with other epigenetic modifiers, particularly PRMT5, to modulate tumor progression and therapeutic response." (PMID 41346390, 2025). "Interestingly, in Case 10, GTOs (whose patient-derived tumor was MGMT-methylated) were responsive to TMZ; however, they were not responsive to MTIC, the active metabolite of TMZ." (PMID 41155119, 2025). "Preclinical studies have demonstrated that KL-50 induces DNA interstrand crosslinks selectively in MGMT-silenced tumor models and retains activity in the absence of functional MMR, highlighting its potential to fill a critical therapeutic gap in recurrent, treatment-refractory tumors." (PMID 41169667, 2025). "MGMT analysis was not feasible in 5 patients (7.0%) due to inadequate tumor material." (PMID 40310485, 2025). "At six-month follow-up, tumor progression distribution revealed 11 IDH mutant and 13 IDH wildtype cases in the MGMT methylated group (total 24 progressions), compared to 11 IDH mutant and 17 IDH wildtype cases in the MGMT unmethylated group (total 28 progressions)." (PMID 40927528, 2025).
tumor (continued). "In tumor cells, TMZ chemoresistance is mainly attributed to the activation of DNA damage repair pathways, including homologous recombination repair, nonhomologous end joining, mismatch repair, base excision repair, and O6-methylguanine DNA methyltransferase (MGMT)-mediated DNA methyl adduct removal." (PMID 41390817, 2025). "Certain mutations were more frequently observed in MGMT IHC negative tumors, particularly those involving genes that regulate the cell cycle, such as DAXX and CDKN2A, which were altered in only primary tumor specimens." (PMID 39825572, 2025). "However, the identified associations between MR imaging AI-generated volumes and PFS were independent of tumor location, MGMT methylation status, or extent of resection, providing valuable insights for risk stratification." (PMID 39001264, 2024). "Numerous studies have shown that the effect of TERT mutations on prognosis depends on an assortment of variables, including age, tumor histology, the absence of IDH mutations, and the existence of an unmethylated O6-methylguanine-DNA-methyltransferase (MGMT) promoter." (PMID 38932383, 2024). "However, they noted the significant presence of MGMT unmethylated patients who underwent subtotal tumor resection, a factor the authors acknowledged but did not take into account in their analysis." (PMID 38116137, 2024). "Furthermore, certain factors are associated with reduced response to resection with adjuvant chemoradiation, such as IDH-wildtype GBM without methylguanine methyltransferase (MGMT) promoter methylation, poor tumor excisability, and resistance to chemotherapy." (PMID 38893250, 2024). "We collected clinicopathological data, including tumor pathological grading, staging, serum concentrations of neuron-specific enolase (NSE) and pro-gastrin-releasing peptide, levels of inflammatory factors, and expression of oxygen 6-methylguanine-DNA methyltransferase (MGMT)." (PMID 39061142, 2024). "MGMT-methylation has no substantial effect on tumor response to CTx." (PMID 38827324, 2024). "Notably, we observed a reverse correlation between the expression of O6-methylguanine methyltransferase (MGMT)—a protein responsible for repairing methylated guanine and thus protecting chromosomes from alkylating agents like TMZ —and the tumor response to PEG~TLZ+TMZ." (PMID 38893160, 2024). "Owing to cost-effectiveness and technical constraints, tumor-related biomarkers, such as MGMT, which could directly impact prognosis, were not included in the study, potentially weakening its robustness." (PMID 39330000, 2024). "Variables associated with longer survival in the multivariable model were MGMT promoter hypermethylation, non-central tumor location, complete resection of enhancing tumor, WHO performance status 0–1, unilateral tumor location, fewer lobes involved, younger age and no comorbidities." (PMID 37711136, 2023). "Molecular stratification showed that the survival benefit was owed to patients with MGMT promoter methylation (MGMTpos) who received tumor-specific therapy as opposed to BSC (6.2 vs. 2.6 months, p < 0.001), especially to those with better clinical status and no initial polypharmacy." (PMID 37289281, 2023). "The reasoning is based on the fact that temozolomide is not only safe and easy to take, but is also expected to improve survival in a clinically important way for 30-40% of patients who are expected to have an MGMT-methylated tumor, for which there are no better treatment options." (PMID 37881322, 2023).